PDE4A (phosphodiesterase 4A)
Diseases named in the same sentence as PDE4A in open-access papers (continued):
Sharing a sentence is not in itself a finding about the gene and the disease.
uveitis (2 papers, 2020 to 2025). An inflammatory process affecting a part of or the entire uvea. "Furthermore, there was a significant correlation between patients’ age-specific regulation of genes MYLIP and PDE4A in the uveitis only group and CCR7, LBH, and LCK in the systemic disease-associated uveitis group." (PMID 40270958, 2025). "For instance, in the uveitis only group, the genes KLHL21, MYLIP, ZNFX1, PDE4A, TNFRSF21, and N4BP2L2 were downregulated, while METTL72, GAPT, CD180, CCR2, and TLR7 were upregulated when comparing uveitis patients with healthy controls." (PMID 40270958, 2025). "Another target of immunotherapy herein predicted as uveitis classifier is the gene PDE4A, coding for the intracellular non-receptor enzyme, phosphodiesterase 4A, known to modulate inflammation, including T cell-induced inflammation." (PMID 40270958, 2025).
breast tumor (1 paper, 2016). "As there are four isotypes (PDE4A, 4B, 4C and 4D) in PDE4 family, we analyzed the expression of PDE4 isotypes in various breast tumor types with TCGA dataset." (PMID 27901486, 2016).
cholangiocarcinoma (1 paper, 2023). A carcinoma that arises from the intrahepatic biliary tree (intrahepatic cholangiocarcinoma) or from the junction, or adjacent to the junction, of the right and left hepatic ducts (hilar cholangiocarcinoma). "For example, PDE4A was expressed significantly higher in stomach adenocarcinoma rather than in normal stomach tissue, and it was expressed significantly higher in cholangiocarcinoma rather than in normal biliary tract tissue, which suggested a crucial role of PDE4A in cancer progression." (PMID 37251402, 2023).
esophageal squamous cell carcinoma (1 paper, 2025). Esophageal squamous cell carcinoma (ESCC) is a type of esophageal carcinoma (EC) that can affect any part of the esophagus, but is usually located in the upper or middle third. "PDE4A showed a critical role in the progression of esophageal squamous cell carcinoma (ESCC) through its regulation by lncRNA HCP5." (PMID 40129976, 2025).
fibrosarcoma (1 paper, 2024). A malignant mesenchymal fibroblastic neoplasm affecting the soft tissue and bone. "Significant degradation of endogenously expressed PDE4A longforms was observed after 6 h treatment with the PDE4 SNIPER in HT1080 cells (human epithelial cells from fibrosarcoma patient), and this could be rescued by pretreatment with a proteasome inhibitor validating the mechanism of action." (PMID 39673076, 2024).
keloid (1 paper, 2024). An irregularly shaped, elevated mark on the skin caused by deposits of excessive amounts of collagen during wound healing. "The analysis of PDE4 subtypes showed PDE4B the most overexpressed in keratinocytes from hypertrophic scars and keloids followed by PDE4D expression and in a lesser extent by PDE4A and PDE4C." (PMID 39223490, 2024).
malaria (1 paper, 2023). Malaria is a serious and sometimes fatal disease caused by a parasite that commonly infects a certain type of mosquito which feeds on humans. "KEGG analysis showed that upregulated genes in the PDE4A high-expression group were enriched in complement and coagulation cascades and malaria, while downregulated genes in NSCLC were enriched in retinol metabolism and drug metabolism-cytochrome P450." (PMID 37251402, 2023).
narcolepsy (1 paper, 2024). A sleep disorder characterized by a tendency for excessive sleepiness during the day which occurs even after adequate sleep in the nighttime. "Furthermore, rs2305795 and rs11085752, upstream and downstream of PDE4A, respectively, have been shown to contribute to the genetic risk of neurological diseases, i.e., narcolepsy and Alzheimer’s." (PMID 38540428, 2024).
oral submucous fibrosis (1 paper, 2025). "Previous research by the authors highlighted that arecoline, a known risk factor for OSCC, increases phosphodiesterase-4A (PDE4A) activity in TGFβ activated buccal mucosal fibroblasts, which contributes to the development of oral submucous fibrosis (OSF), a precancerous condition." (PMID 39857718, 2025).
osteoarthritis (1 paper, 2023). A noninflammatory degenerative joint disease occurring chiefly in older persons, characterized by degeneration of the articular cartilage, hypertrophy of bone at the margins and changes in the synovial membrane. "Alternatively, six of the top concordant genes (HTR7, TRAK1, LAMA4, HS6ST1, PDE4A, GPNMB) at 52 weeks have been documented in prior osteoarthritis literature." (PMID 37134114, 2023).
papillary thyroid carcinoma (1 paper, 2024). "We found that the patients with more aggressive forms of papillary thyroid carcinoma, such as CCVPTC, exhibited up-regulated PDE4C expression and down-regulated PDE4A/B/D expression compared with PTC and FVPTC." (PMID 38514754, 2024).
polycythemia vera (1 paper, 2024). "Similarly, PDE4A expression decreased in CD34+ granulocytes taken from patients with essential thrombocytopenia, polycythemia vera, and primary myelofibrosis." (PMID 38514754, 2024).
Tetralogy of Fallot (1 paper, 2024). A congenital cardiac malformation comprising pulmonary stenosis, overriding aorta, ventricular septum defect, and right ventricular hypertrophy. "PDE3A (Phosphodiesterase 3A, 123805) together with PDE4 (Phosphodiesterase 4A, 600129) has been shown to control the intracellular cAMP and cardiac excitation–contraction coupling, which were further confirmed to be associated with Tetralogy of Fallot, validating our prediction." (PMID 39202774, 2024).
cancer (42 papers, 2012 to 2025). A tumor composed of atypical neoplastic, often pleomorphic cells that invade other tissues. "As for NSCLC, PDE4A expression also showed a significant positive correlation with cancer-associated fibroblast in all methods: EPIC (R = 0.414, p < 0.001), MCPCOUNTER (R = 0.396, p < 0.001), XCELL (R = 0.252, p < 0.001), and TIDE (R = 0.357, p < 0.001)." (PMID 37251402, 2023). "As for NSCLC, PDE4A expression also showed a significant positive correlation with cancer-associated fibroblast." (PMID 37251402, 2023). "Interestingly, we also observed that PDE4A expression showed a significant positive correlation with cancer-associated fibroblast in most cancer types." (PMID 37251402, 2023). "Interestingly, PDE4A expression showed a significant positive correlation with cancer-associated fibroblast in most cancer types." (PMID 37251402, 2023). "Recently, accumulating researches suggest a potential role for PDE4A in cancer development, highlighting its complex influence across physiological process." (PMID 40129976, 2025). "Dysregulation of PDE4 activity has been implicated in numerous pathological conditions, including neurodegenerative diseases, inflammatory disorders, and certain cancers, making PDE4 a promising therapeutic target." (PMID 39942796, 2025). "We found that the PDE4A expression level in cancer specimens obtained from 110 patients with stage III THCA was lower than that in 284 patients with stage I THCA." (PMID 38514754, 2024). "RALGPS1, NUDT9, NUDT2, and PDE4A were less expressed in cancer cell lines; JUP, ADA, HPRT1, and IMPDH1 were highly expressed in cancer cell lines in CCLE." (PMID 34745385, 2021). "But the research of PDE4 inhibitors in cancer mainly surround PDE4A, PDE4B, and PDE4D28." (PMID 38514754, 2024). "This makes PDE4 a promising target in cancer treatment strategies." (PMID 38474160, 2024). "As one of the four isoforms of PDE4, phosphodiesterase 4A (PDE4A) is associated with expression in various cancers and its involvement in VEGF-mediated angiogenesis accelerates epithelial mesenchymal transformation in cancer." (PMID 36278172, 2022). "Indeed, it seemed that PDE4A was differentially expressed in diverse cancer types." (PMID 37251402, 2023). "The expression levels of PDE4A, PDE4B and PDE4D were down-regulated in THCA patients at different cancer stages, while the expression level of PDE4C was significantly up-regulated." (PMID 38514754, 2024).
tumor (29 papers, 2014 to 2025). "Regarding the PLR-associated genes, PDE4A is a predicted target of miR-4644 and miR-7106-5p, which is suggested to regulate levels of cAMP, an immune suppression agent also involved in tumor pathology." (PMID 37950349, 2024). "This may be caused by the regulation of PDE4A in VEGF-mediated epithelial-to-mesenchymal transition (EMT) during tumor progression." (PMID 35433477, 2022). "Further research is needed in the future to clearly define the specific role of PDE4A in tumor development and its potential therapeutic implications." (PMID 40129976, 2025). "In summary, PDE4A not only acts directly on tumor cells to promote their growth but also influences the tumor microenvironment." (PMID 40129976, 2025). "Survival analysis showed NSCLC patients with higher PDE4A expression levels had worse prognoses, indicating the pro-tumor role of PDE4A." (PMID 37251402, 2023). "PDE4A has been reported to be involved in the regulation of tumor suppressor genes in tumors and hematological malignancies." (PMID 35433477, 2022). "A comparison of 23 clinical oral and throat cancers and 24 normal oral tissue samples (GSE107591) also reported that PDE4A was significantly up-regulated in tumor samples." (PMID 34819854, 2021). "Studies show that there is an interaction between PDE4A and HIF1α in tumor cells." (PMID 40129976, 2025). "However, PDE4A may be protumorigenic or antitumorigenic, depending on the type of tumor or the type of tumor cells." (PMID 40129976, 2025). "Next, we speculated whether PDE4A had different expression patterns in normal and tumor tissues." (PMID 37251402, 2023). "In A549 adenocarcinoma cells, the expression of PDE4A and PDE4D increase under hypoxic conditions and enhance HIF signaling, which promotes the proliferation of tumor cells." (PMID 40129976, 2025).
infection (11 papers, 2011 to 2025). The state of being infected such as from the introduction of a foreign agent such as serum, vaccine, antigenic substance or organism. "The expression of PDE4A was similarly elevated at 8 weeks and was somewhat lower at 12 weeks post-infection." (PMID 21949656, 2011). "At 4 weeks post-infection, low basal levels of expression of TNF-α and PDE4A were noted in comparison with uninfected animals." (PMID 21949656, 2011).
cardiovascular diseases (10 papers, 2018 to 2026). "Despite the fact that PDE4A, PDE4B and PDE4D are expressed in the human and rodent heart, with PDE4D being the predominant isoform found in the human heart, there is no approval for a PDE4 inhibitor for the treatment of cardiovascular diseases." (PMID 29461511, 2018).
brain disorder (1 paper, 2024). A disease affecting the brain or part of the brain. "PDE4D longform selective, allosteric compounds are under investigation for a range of brain disorders and their selectivity arises from a single amino acid difference (PDE4D vs PDE4A, 4B, 4C) in the UCR2 region." (PMID 39673076, 2024).
hematologic tumors (1 paper, 2025). "PDE4A is significantly upregulated in several hematologic tumors, stomach adenocarcinoma, and cholangiocarcinoma, and is associated with cell proliferation." (PMID 40129976, 2025).
PDE4A also shares sentences with these, for which no sentence is quoted: chronic obstructive pulmonary disease (145 papers); psoriasis (82); atopic dermatitis (40); Alzheimer disease (23); Cognitive impairment (23); inflammatory bowel disease (19); respiratory diseases (19); lung fibrosis (18); autoimmune disease (16); plaque psoriasis (16); neurological disorders (13); rheumatoid arthritis (13); chronic bronchitis (12); lung diseases (11); memory impairment (11); Sepsis (11); Arthritis (10); metabolic disorders (10); psychiatric disorder (8); Stroke (8); airway hyperresponsiveness (7); neurodegenerative disease (7); alcohol use disorder (6); colitis (6); diabetes (6); liver fibrosis (6); Oral ulcer (6); Parkinson disease (6); colorectal cancer (5); cystic fibrosis (5).
A further 189 diseases each share a sentence with PDE4A in 5 papers or fewer.